PTCSC1 (papillary thyroid carcinoma susceptibility candidate 1)
Synonyms: AK023948; NCRNA00197; PTCSC
Gene: Long non-coding RNA gene on chromosome 8 (133,054,959 to 133,057,767, forward strand). Ensembl gene ENSG00000287736.
Diseases named in the same sentence as PTCSC1 in open-access papers:
PTCSC1 is named in the same sentence as 5 diseases in open-access papers, as found by Europe PMC text mining. Sharing a sentence is not in itself a finding about the gene and the disease. The quoted sentences say what the papers report.
thyroid cancer (3 papers, 2018 to 2025). "Recently, a class of long intergenic noncoding RNAs named papillary thyroid cancer susceptibility candidate (PTCSC), such as PTCSC1 (located in 8q24), PTCSC2 (located in 9q22) and PTCSC3 (located in 14q13), might predispose infected persons to thyroid cancer." (PMID 29416703, 2018).
tumor (2 papers, 2022 to 2025). "Furthermore, compared to African American samples, the downregulation of PGF and PTCSC1 in White PTC samples suggests potential differences in tumor aggressiveness." (PMID 40558258, 2025).
PTCSC1 also shares sentences with these, for which no sentence is quoted: papillary thyroid cancer (2 papers); breast tumour (1); thyroid tumor (1).